INS (insulin)
Diseases named in the same sentence as INS in open-access papers (continued):
Sharing a sentence is not in itself a finding about the gene and the disease.
diabetes (continued). "The Restoring Insulin Secretion (RISE) study found that youth with recently diagnosed diabetes and IGT compared with their adult counterparts have lower insulin clearance, assessed by the ratio of fasting C‐peptide to fasting insulin, in the presence of greater β‐cell function." (PMID 40470991, 2025). "Accordingly, diabetes mellitus (both type 1 and type 2) patients carrying chronic defective insulin signaling in the keratinocytes often suffer non-healing wounds and foot ulcers." (PMID 40277891, 2025). "Among the patients with HS, those with diabetes mellitus (n = 17) showed significantly altered insulin–glucose homeostasis compared to those without diabetes (n = 78)." (PMID 40217596, 2025). "In individuals without diabetes, we observed a generally balanced relationship between insulin demand and adequacy in children and adults but an imbalanced relationship in adolescents." (PMID 39611962, 2025). "The median baseline diabetes knowledge scores of those on insulin and not on insulin were 16.0 (IQR 13.0-18.0) out of 22 and 9.0 (IQR 8.0-11.0) out of 14, respectively." (PMID 40340926, 2025). "An important founding was that by administration of insulin these changes were significantly improved, independently of other indices of diabetes, such as glycated hemoglobin, that did not correct." (PMID 39997711, 2025). "Eating healthy diet and regular physical exercise are nonpharmacological approaches to manage diabetes whereas insulin therapy in addition to oral antidiabetic agent of classes sulfonylureas and biguanides are commonly used pharmacological agent." (PMID 39803296, 2025). "Despite extensive research and various interventions designed to improve adherence to treatment of chronic conditions, medication non-adherence persists among patients with diabetes, including those prescribed insulin, leading to poor health outcomes." (PMID 39854487, 2025). "When diabetes progresses to the point that several non-insulin glucose-lowering medications are no longer effective in providing individuals with adequate glucose management, the initiation of insulin is recommended." (PMID 39820580, 2025). "First, the broad inclusion criteria, which considered patients with varying durations of diabetes, both insulin- and noninsulin-treated, and with a clinically relevant and realistic HbA1c spectrum, provided a not overselected patient population." (PMID 40344662, 2025). "Type 2 diabetes mellitus (DM2) results from defects in the insulin molecule or from altered cell receptors for insulin and represents impaired insulin function (insulin resistance) rather than deficiency." (PMID 39841769, 2025). "This case fits the definition because the patient developed diabetes at the age of 46 years and did not require insulin treatment for a long time, despite having high GADA levels." (PMID 40226121, 2025). "The onset of diabetes is most of the time slow and without ketoacidosis, insulin requirement is low, and microvascular and macrovascular complications are rare." (PMID 40988749, 2025). "In individuals without diabetes, pancreatic β cells within the islets of Langerhans dynamically secrete insulin to maintain stable glucose levels." (PMID 40742490, 2025). "Diabetes mellitus (DM) is a chronic metabolic disorder characterized by persistent hyperglycemia resulting from insufficient or absent insulin secretion by the pancreas, or insulin resistance." (PMID 40046369, 2025). "We have demonstrated that while systemic administration of pMSCs does not improve insulin sensitivity in STZ-induced diabetic mice, they are effective in preventing the progression of diabetes-associated microvascular complications." (PMID 40869378, 2025). "GPRC5B, an obesity-related membrane protein implicated in insulin resistance, may contribute to the metabolic disturbances characteristic of type 2 diabetes mellitus (T2DM), including increased adiposity, impaired insulin secretion, and glucose intolerance." (PMID 40864777, 2025).
diabetes (continued). "DEPS‐10 is a shortened version of the DEPS‐R without insulin‐specific items, allowing screening of disordered eating regardless of diabetes type and treatment regimen." (PMID 40440439, 2025). "The most common type 2 diabetes mellitus (DM), usually in adults, occurs when the body resists or does not produce enough insulin." (PMID 40760593, 2025). "On the contrary there were no signs of different distribution of age, insulin delivery method, daily frequency of blood glucose measurements, HbA1c, or diabetes duration among the low, medium, and high CHI groups." (PMID 41212850, 2025). "The lack of insulin production and glucagon secretion makes glycemic control difficult in this form of diabetes, which gives it the name “brittle” diabetes." (PMID 40559084, 2025). "At 1 year, shorter T2DM duration (odds ratio [OR]: 0.76; 95% confidence interval [CI]: 0.68–0.84; p < 0.001) and absence of insulin use (OR: 0.29; 95% CI: 0.10–0.84; p = 0.023) were significant predictors of diabetes remission." (PMID 41231326, 2025). "Unlike other diabetes models that target specific UPR pathways or insulin processing, mFicDR371S mice represent a model where global ER stress regulation is impaired." (PMID 40073934, 2025). "Diabetes mellitus (DM) is a long-term metabolic condition marked by elevated blood glucose levels resulting from complete or partial absence of insulin production and secretion, insulin resistance, or a combination of these defects." (PMID 40988828, 2025). "Glycated hemoglobin (HbA1c) at study end was significantly higher in mice with diabetes treated with vehicle (D-Pal) compared to non-diabetic mice (ND) and diabetic mice treated with insulin (D-Ins)." (PMID 40575255, 2025). "A study revealed that the majority of diabetes patients treated with insulin in Thailand did not store their insulin at the correct temperature." (PMID 40817200, 2025). "Diabetes has been tied to accelerated damage to the brain, not entirely mediated by microvascular injury, but also due to insulin’s role in memory and other cognitive processes." (PMID 41470842, 2025). "The Chinese Diabetes Society’s seven-domain model (CDS-7) offers a comprehensive framework for pediatric self-management, spanning knowledge, diet, decision-making, glucose monitoring, insulin use, physical activity, and psychosocial well-being." (PMID 41339733, 2025). "In conclusion, this study showed that the age-related high prevalence of diabetes and IGT is associated with impaired insulin secretion rather than insulin resistance in Japanese individuals." (PMID 40002793, 2025). "Seven of our participants were treated with insulin until their death and the 8th patient was lost to follow‐up, thus it is not known if the diabetes had persisted." (PMID 40887432, 2025). "Antidiabetic drugs that improve insulin sensitivity might not only manage metabolic symptoms in PCOS and type 2 diabetes mellitus but may also alleviate depressive symptoms and reduce suicide risk." (PMID 40457354, 2025). "Adjusted for age sex, BMI, physical activity, smoking status, diabetes duration, pre-existent macrovascular and microvascular complications, SBP, serum LDL-C, use of insulin, aspirin and statins, number of antihypertensive drugs in use, HGI and HbA1c parameters." (PMID 41282290, 2025). "On the other hand, CaHMB-enriched supplements, especially combined with amino acids like lysine and arginine, have been shown in cellular and diabetes rodent models to increase GLUT4 expression and Akt signaling, enhance glucose uptake, improve insulin sensitivity, and preserve lean mass." (PMID 41156461, 2025). "Among the 94 residents with diabetes, 37.2% were not receiving any antidiabetic treatment, 43% were on insulin, and 25% were receiving oral antidiabetic agents." (PMID 40128462, 2025). "Diabetes mellitus (DM) is a metabolic disorder resulting either from the lack of insulin, impaired insulin action or both, eventually resulting in hyperglycemia." (PMID 40964503, 2025).
diabetes (continued). "Non-insulin diabetes medications were taken by 60.2% (115/191), non-insulin diabetes medications and insulin were taken by 35.6% (68/191), and 3.7% (7/191) were on insulin therapy only." (PMID 40087464, 2025). "Inhibited EGFR/PI3K/AKT signaling pathway, reduced the released of inflammatory factors IL-1β, IL-6, TNF-αImproved lipid and glucose metabolism, promoted adipogenesis, improved insulin sensitivity by regulating PI3K-Akt signaling pathway, and fight against diabetes and its complications." (PMID 41356003, 2025). "None of the 11 patients assessed had a diagnosis of diabetes, suggesting that the local insulin-specific responses seen were related to lymphedema." (PMID 40821816, 2025). "Insulin-treated diabetes had more comorbidities than non-insulin-treated diabetes and was prone to more revascularization procedures." (PMID 40810069, 2025). "Our patient had no history of diabetes, seizure disorders, oral hypoglycemic agents, insulin use, or critical illness to explain her profound hypoglycemia." (PMID 40757084, 2025). "Immunofluorescence microscopy was performed for insulin, glucagon, and somatostatin presence on paraffin-embedded sections of pancreata from 20 donors without diabetes aged between 11 days and 79 years of age." (PMID 39791735, 2025). "A single dose of glutamine (30 g) is sufficient to increase both fasting and postprandial circulating concentrations of GLP‐1, glucagon, and insulin in both lean and obese individuals, regardless of diabetes status." (PMID 40289598, 2025). "Type 1 diabetes mellitus (T1D or T1DM) is an organ-specific autoimmune disease characterized by the gradual, immune-mediated destruction of insulin-secreting pancreatic beta cells, which ultimately leads to lifelong dependence on exogenous insulin." (PMID 40843763, 2025). "Others were unaware of critical practices, such as homogenizing NPH insulin before use, not using expired strips, and properly disposing of diabetes supplies." (PMID 40008736, 2025). "There are many medications available to control blood sugar levels that do not completely cure diabetes, but focus on controlling or adjusting insulin secretion." (PMID 39931095, 2025). "Type 1 Diabetes Mellitus (T1DM) results from complex interactions among genetic, autoimmune, and environmental factors, leading to the autoimmune destruction of pancreatic beta cells, which substantially reduces or eliminates insulin production." (PMID 40564753, 2025). "Type 2 diabetes mellitus (T2DM), formerly referred to as “non-insulin-dependent” or “adult-onset” diabetes, results from the body’s inability to use insulin effectively." (PMID 40648505, 2025). "Variables significantly associated with insulin discontinuation in the multivariate Cox proportional hazard model were shorter diabetes duration, lower HbA1c at baseline, absence of microangiopathy and lower baseline insulin doses." (PMID 40277315, 2025). "It offers important data on early-phase insulin secretion, which is usually the first to be affected during the initial stages of diabetes but does not reflect the overall glucose tolerance." (PMID 39857881, 2025). "Injection hold time was significantly related to duration of diabetes (p = 0.033), insulin therapy duration (p = 0.049), and age (p = 0.041), but not to device type (p = 0.089)." (PMID 41306599, 2025). "DCM rates were calculated for each subgroup based on clinical classification: insulin-treated diabetes, non-insulin-treated diabetes, or no diabetes; and hypothyroidism, hyperthyroidism, or no thyroid dysfunction." (PMID 41153651, 2025). "Although automated insulin delivery systems are at the forefront of diabetes research, fully closed-loop systems that do not require CC remain in development and are not yet available for people with T1D." (PMID 40153793, 2025).
diabetes (continued). "Continuous intraperitoneal insulin infusion (CIPII) is an option for insulin-treated patients with impaired subcutaneous insulin absorption and/or extreme swings in blood glucose despite optimal diabetes management." (PMID 40995084, 2025). "For diabetes management, detailed national guidelines were available in 30% (3/10) of FCVs compared with 83% (10/12) of non-FCVs; insulin was available in primary care in 50% (5/10) of FCVs compared with 83% (10/12) of non-FCVs." (PMID 41338627, 2025). "Our review provides a comprehensive summary of non-insulin-mediated and insulin-mediated hypoglycemia in adult patients without diabetes." (PMID 40648766, 2025). "In our registry, the incidence of diabetes mellitus was similar between sexes, with a non-significant increase in the insulin-requiring subtype." (PMID 39756819, 2025). "This study aimed to investigate the association between ApoB levels and glycemic parameters, including fasting glucose, insulin resistance, and glycated hemoglobin (HbA1c), in individuals without diagnosed diabetes." (PMID 40423035, 2025). "Using this acute model for inducing diabetes, we confirmed our previous discovery of a major role for the heparan sulfate (HS)-degrading enzyme HPSE-1 in islet inflammation and immune-mediated damage of insulin-producing beta cells." (PMID 40362360, 2025). "In addition, although the barriers to diabetes medication adherence selected in this study were based on relevance to the focus group participants, the order of relevance may differ in other Latin American populations living elsewhere in the United States or with a different insulin usage profile." (PMID 40311126, 2025). "Insulin therapy was initiated in four patients without diabetes for hyperglycaemia correction during hospital stay but was discontinued before discharge." (PMID 40507430, 2025). "Therefore, increasing the presence of butyrate-producing bacteria may improve insulin sensitivity and metabolic abnormalities, providing a theoretical basis for further investigation into the impact of F. plautii and butyric acid production on the pathogenesis of pre-diabetes." (PMID 40488467, 2025). "Assessment of day 2 glycaemia may provide a truer indicator of the quality of diabetes care and associated benefits, 12 although we acknowledge that the glucose threshold for adverse outcomes does not necessarily determine the threshold for insulin intervention in a hospital setting." (PMID 39809558, 2025). "Our finding that non-insulin-treated diabetes is associated with the highest odds of dilated cardiomyopathy aligns with these mechanistic insights, suggesting that early metabolic changes—even before escalation to insulin therapy—may predispose to structural remodelling." (PMID 41153651, 2025). "In the context of diabetes, ADGRL2 may influence insulin signaling pathways, adipogenesis, and inflammation, which are critical in glucose homeostasis." (PMID 39941463, 2025). "Once back in their own home, PWDI are likely to require adjustments in their insulin requirements; however, referral to the community diabetes team was not automatic." (PMID 40324886, 2025). "Cross-disease metabolic synergy: Beyond diabetes, the DASH diet shows efficacy in managing gestational diabetes, polycystic ovary syndrome (PCOS), and diabetic retinopathy through its anti-inflammatory, antioxidant, and insulin-sensitizing properties." (PMID 41229546, 2025). "Within this cohort, 23 (21%) discontinued insulin entirely, while 38 (35%) discontinued at least one non-insulin diabetes medication." (PMID 40700264, 2025). "Notably, this association remained significant even after adjustment for known predictors of insulin resistance, such as age, sex, diabetes duration, BMI, plasma triglycerides, CKD, LSM and glycaemic control, including daily insulin dose." (PMID 40083078, 2025).
diabetes (continued). "The DEPS‐R is only suitable for people with rapid‐acting insulin treatment, which has led to a lack of diabetes‐specific screening for many people with type 2 diabetes." (PMID 40440439, 2025). "Type 2 diabetes mellitus (T2DM), commonly referred to as one of the modern lifestyle diseases, is characterized by elevated blood glucose levels resulting from increased insulin resistance and impaired function of insulin and other glucose-regulating hormones." (PMID 41157216, 2025). "The diabetic stage can be further subdivided into three clinical substages: diabetes that does not require insulin, diabetes that requires insulin for glycemic control, and diabetes that requires insulin for survival." (PMID 40732323, 2025). "These efforts reflect a growing recognition that the most effective artificial pancreas is not merely one that automates insulin but one that aligns with the lived experience of diabetes." (PMID 40718205, 2025). "It is important to note that the HOMA-IR index is not applicable to patients with diabetes mellitus who are undergoing insulin treatment." (PMID 40564010, 2025). "Demographic characteristics at baseline, including age, sex and insulin-treated diabetes patients, were not statistically different between the two groups." (PMID 40008349, 2025). "The prevalence of diabetes among the 464 non-transplanted adults with CF followed at Cochin CF center in 2019 was 18 % (n = 83); 72 were treated with insulin (15 %) and were eligible for inclusion." (PMID 40688702, 2025). "Dipeptidyl peptidase 4 inhibitors (DPP-4i) (sitagliptin, vildagliptin, and linagliptin) have been shown to enhance insulin resistance in patients with type 2 diabetes mellitus by mitigating macrophage-induced inflammation without affecting insulin secretion." (PMID 40564010, 2025). "During the compensatory phase of diabetes (i.e., hyperinsulinemia), IRMs secrete VEGF-A to promote angiogenesis, supporting islet hypertrophy and increased vascular density, thereby maintaining β-cell insulin secretion." (PMID 40791590, 2025). "One of the biggest obstacles in gene therapy, which is one of the therapeutic modalities that is expected to entirely cure diabetes, is that fully developed β-cells are not available for insulin replacement therapy." (PMID 39453501, 2025). "We found that bi-hormonal cells containing glucagon/insulin, insulin/somatostatin, or glucagon/somatostatin each represented around 2–3% of total islet endocrine cells in individuals without diabetes or other metabolic diseases." (PMID 39791735, 2025). "The insulin pump was never interrupted and continued with the support of the diabetes team, achieving optimal glycemic control throughout the postpartum period until the acute condition resolved with a time in range (70-180 mg/dL) of 88%." (PMID 41356922, 2025). "Background/Objectives: Muscle loss is a serious complication in chronic disease patients, yet studies on long-term changes in muscle mass based on insulin sensitivity in the absence of diabetes mellitus are scarce." (PMID 40004800, 2025). "Diabetes Mellitus (DM) is a serious chronic medical condition that occurs either when the pancreas fails to generate enough insulin or when the body fails to use it effectively." (PMID 41427159, 2025). "In the present study, we examined the expression levels of NGF and Sirt1 in human pancreatic tissue specimens and found that they were lower in islet β cells in patients with diabetes than in those without and inversely correlated with insulin secretion." (PMID 41181709, 2025). "The effect of ILI was assessed after stratification for remission eligibility at baseline (diabetes duration ≤6 years and no insulin therapy)." (PMID 40707395, 2025). "This study aims to investigate the effects of diabetes mellitus on myocardial inflammation, oxidative stress, and protein quality control (PQC) mechanisms in HFpEF, with particular emphasis on insulin signaling, autophagy, and chaperone-mediated stress responses." (PMID 40369521, 2025).